ALDOB (aldolase, fructose-bisphosphate B)
Description:
Catalyzes the aldol cleavage of fructose 1,6-biphosphate to form two triosephosphates dihydroxyacetone phosphate and D-glyceraldehyde 3-phosphate in glycolysis as well as the reverse stereospecific aldol addition reaction in gluconeogenesis. In fructolysis, metabolizes fructose 1-phosphate derived from the phosphorylation of dietary fructose by fructokinase into dihydroxyacetone phosphate and D-glyceraldehyde.
Synonyms: ALDB; ALDO2
Tractability: Small molecule: it has a high-quality binding pocket. PROTAC: ubiquitination databases record sites on it; its protein half-life has been measured.
Gene: Protein-coding gene on chromosome 9 (101,420,560 to 101,449,664, reverse strand). Ensembl gene ENSG00000136872.
Subcellular location: Cytoplasm, cytosol; Cytoplasm, cytoskeleton, microtubule organizing center, centrosome, centriolar satellite
Pathways (Reactome):
Metabolism: Fructose catabolism; Gluconeogenesis; Glycolysis
Disease: Hereditary fructose intolerance
Gene Ontology:
Molecular function: ATPase binding; cytoskeletal protein binding; fructose binding; fructose-1-phosphate aldolase activity; fructose-bisphosphate aldolase activity; identical protein binding; molecular adaptor activity; protein binding
Biological process: fructose 1,6-bisphosphate metabolic process; fructose metabolic process; glycolytic process; negative regulation of pentose-phosphate shunt; vacuolar proton-transporting V-type ATPase complex assembly; canonical glycolysis; gluconeogenesis; fructose catabolic process
Cellular component: centriolar satellite; cytosol; extracellular exosome; microtubule organizing center
Genetic constraint (gnomAD): Loss-of-function variants: 35 observed, 39.22 expected, observed/expected ratio (o/e) 0.89, 90% interval 0.68 to 1.18. The upper end of that interval is the gene's LOEUF score, 1.18, which puts it in group 5 of 6, group 1 being the genes least tolerant of losing a copy. Missense variants: 490 observed, 446.52 expected, observed/expected ratio (o/e) 1.1, 90% interval 1.02 to 1.18. Synonymous variants: 165 observed, 166.83 expected, observed/expected ratio (o/e) 0.99, 90% interval 0.87 to 1.12.
Gene-disease validity (ClinGen):
ClinGen rates the evidence that ALDOB causes each of these diseases.
hereditary fructose intolerance (autosomal recessive): Definitive. Hereditary fructose intolerance (HFI) is an autosomal recessive disorder of fructose metabolism, resulting from a deficiency of hepatic fructose-1-phosphate aldolase activity and leading to gastrointestinal disorders and postprandial hypoglycemia following fructose ingestion.
Homologues: Orthologues: chimpanzee ALDOB (99% identical), macaque ALDOB (99% identical), rabbit ALDOB (97% identical), dog ALDOB (96% identical), rat Aldob (96% identical), mouse Aldob (96% identical), guinea pig ALDOB (96% identical), pig ALDOB (95% identical), zebrafish aldob (76% identical), tropical clawed frog aldob (74% identical), Drosophila melanogaster Ald1 (63% identical), Caenorhabditis elegans aldo-2 (60% identical), and 2 more. Paralogues in human: ALDOC (70% identical), ALDOA (70% identical).
Diseases named in the same sentence as ALDOB in open-access papers:
ALDOB is named in the same sentence as 82 diseases in open-access papers, as found by Europe PMC text mining. Sharing a sentence is not in itself a finding about the gene and the disease. The quoted sentences say what the papers report.
fructose intolerance (16 papers, 2014 to 2025). "Diagnostic assessments identified hereditary fructose intolerance (HFI) with pathogenic variants in the ALDOB gene, along with a diagnosis of celiac disease." (PMID 38929922, 2024). "Low ALDOB expression has been linked to various diseases, including hepatocellular carcinoma, colon adenocarcinoma, and hereditary fructose intolerance (HFI)." (PMID 36978048, 2023). "In the remote sensing and signaling network, ALDOB (fructose-1,6-bisphosphate aldolase) an enzyme involved in sugar metabolism and associated with hereditary fructose intolerance, had the highest betweenness centrality." (PMID 31417100, 2019). "The impaired function of ALDOB has been associated with hereditary fructose intolerance, a recessively inherited disorder of carbohydrate metabolism." (PMID 24968805, 2014). "Indeed, a dual role of F1P to support glycogenesis and induce hepatotoxicity is best observed in patients with hereditary fructose intolerance (HFI) due to ALDOB deficiency." (PMID 39418102, 2024). "Furthermore, ALDOB deficiency has been shown to cause hepatic fat accumulation in humans, as well as hereditary fructose intolerance, which ultimately leads to liver failure." (PMID 39339686, 2024). "Molecular analysis of genomic DNA included (I) exclusion of 3 main ALDOB gene variants causing hereditary fructose intolerance and (II) sequencing analysis of SLC2A5 gene comprising complete coding region, at least 20 bp of adjacent intronic regions and 700 bp of proximal promoter." (PMID 35387598, 2022). "An example for this scenario in our cohort are four patients presenting with a GSD phenotype but two of them were diagnosed as hereditary fructose intolerance (ALDOB gene) and the other two had fructose 1,6 bisphosphatase deficiency (FBP1 gene)." (PMID 41165782, 2025). "To test OREOs beyond our standard fluorescent reporters, we designed circular gRNAs for AldoB148TGA, a mutation that renders the AldoB gene non-functional, causing hereditary fructose intolerance." (PMID 39448590, 2024). "For example, HetExc of the c.448G > C (rs1800546) variant in ALDOB (causes recessive hereditary fructose intolerance) was not statistical significant (P = ∼0.3), despite being observed in the heterozygous state in 627 NFE individuals (AF = ∼0.005)." (PMID 32231685, 2020). "Besides, ALDOB is a key factor of fructolysis, leading to hereditary fructose intolerance (HFI)." (PMID 31450822, 2019). "Intestinal fructose intolerance should not be confused with hereditary fructose intolerance (HFI), which is a severe metabolic disease caused by a mutation in the ALDOB gene." (PMID 34445050, 2021).
hepatocellular carcinoma (15 papers, 2014 to 2025). A malignant tumor that arises from hepatocytes. "Alternatively, given the heterogeneous nature of cancer, aggressive hepatocellular carcinoma is associated with ALDOB downregulation, and stable expression of ALDOB reduced cell migration and lung and intrahepatic metastases." (PMID 34436420, 2021). "Studies have shown that ALDOB-mediated fructose metabolism drives metabolic reprogramming of liver metastases from colon cancer; loss of ALDOB activates insulin receptor(IR) signaling primarily through releasing IR/ALDOB interaction to promote de novo lipogenesis and hepatocellular carcinoma." (PMID 37259038, 2023). "However, in gastric cancer and hepatocellular carcinoma, the opposite effect has been demonstrated, and decreased ALDOB expression was found to be associated with poor prognosis." (PMID 30967137, 2019). "Loss of ALDOB is associated with early recurrence and poor prognosis in hepatocellular carcinoma." (PMID 25929336, 2015). "On the one hand, ALDOB inhibits metastasis through TET1 in hepatocellular carcinoma; on the other hand, it enhances fructose metabolism and drives metabolic reprogramming of colon cancer liver metastasis." (PMID 33282950, 2020). "Downregulation of Aldolase B (ALDOB) has been reported in hepatocellular carcinoma." (PMID 26376879, 2015). "Nonetheless, it should be noted that ALDOB was found to be down-regulated in the progressive stages of hepatocellular carcinoma, probably due to transition of the cancerous cells into utilizing alternative paths for energy sources, for instance – ALDOA overexpression." (PMID 24993527, 2014). "Literature has revealed that abnormal ALDOB expression is closely linked with colorectal cancer (CRC) 12-16 and hepatocellular carcinoma (HCC) 17-19." (PMID 37576390, 2023). "ALDOB downregulation, on the other hand, is associated with multiple malignant characteristics of HCC, partly through TET1 expression, and could thus be considered a prognostic biomarker for hepatocellular carcinoma, particularly at the early stage of disease." (PMID 36276846, 2022). "The glycolytic enzyme fructose 1,6-bisphosphate aldolase B (ALDOB) is aberrantly expressed and impacts the prognosis in hepatocellular carcinoma (HCC)." (PMID 36644641, 2022).
gastric cancer (10 papers, 2014 to 2025). A primary or metastatic malignant neoplasm involving the stomach. "Downregulation of ALDOB has also been observed in gastric cancer patients and this was associated with poor prognosis." (PMID 37371512, 2023). "Previous research revealed a positive association of ALDOB expression with the survival of patients with gastric cancer and ALDOC as a target for positive regulation by the retinoblastoma (RB) tumor suppressor protein." (PMID 37834179, 2023). "Likewise, in gastric cancer, loss of ALDOB correlates with adverse outcomes, while ALDOB re-expression curbs tumor cell growth and migration by suppressing the AKT signaling pathway." (PMID 40520908, 2025). "ALDOB (fructose-1,6-bisphosphate aldolase B) is involved in glycolysis and is significantly downregulated in gastric cancer tissues compared to normal tissues." (PMID 41220952, 2025). "Restoring ALDOB expression improves the sensitivity of gastric cancer cells to various anticancer agents, particularly chemotherapies like talazoparib and FTI-277." (PMID 41220952, 2025). "Specifically, reduced ALDOB expression in gastric cancer tissues activates downstream glycolytic enzymes by lifting inhibition on the AKT signaling pathway, thereby promoting aerobic glycolysis, tumor growth, and metastasis." (PMID 41220952, 2025). "Restoring ALDOB expression enhances the sensitivity of gastric cancer cells to chemotherapy, underscoring its potential as a therapeutic target." (PMID 41220952, 2025). "The precise role of ALDOB in gastric cancer (GC) and the endogenous process is elusive and needs further exploration." (PMID 37576390, 2023). "ALDOB is a metabolic enzyme involved in glycolysis and fructose catabolism, and its expression is abnormal in various cancer types, including gastric cancer, colorectal cancer, clear cell renal cell carcinoma, and liver cancer." (PMID 36644641, 2022). "Compared to normal tissues, ALDOB expression was more than seven-fold lower in gastric cancer tissues." (PMID 36644641, 2022). "Their findings imply that ALDOB might function as a potential molecular indicator for gastric cancer when combined with survival analysis results." (PMID 40852386, 2025). "ALDOB, a key glycolytic enzyme, functions as a tumor suppressor in gastric cancer." (PMID 41220952, 2025). "The transition of malignant tissues into over-expressing ALDOA at the expense of the prevalent Aldolase isozyme in the normal tissue was also reported, along with the decrease of serum ALDOB levels in malignant tissues, including in patients with gastric cancer." (PMID 24993527, 2014). "In contrast, investigations into gastric cancer revealed diminished ALDOB levels within tumor tissues relative to surrounding non-tumor regions." (PMID 40852386, 2025).
colon cancer (9 papers, 2015 to 2023). "This suggests that ALDOB deficiency can inhibit the growth characteristics of colon cancer cells by inhibiting epithelial-mesenchymal transformation, and ALDOB can be used as a new therapeutic target, which is of great significance for the treatment and prognosis of colon cancer." (PMID 37020597, 2023). "The ALDOB protein level has been suggested as a biomarker for predicting postoperative prognosis in CRC patients, as well as the risk of colon cancer liver metastases and the response of rectal cancer patients to neoadjuvant chemoradiation therapy." (PMID 37816733, 2023). "By screening glycolysis-related genes in colon cancer, high expression of ALDOB (ALDOB) was detected in colon cancer cells." (PMID 37020597, 2023). "By gene knockout of ALDOB, the epithelial-mesenchymal transformation was inhibited, and the growth and migration of colon cancer cells were blocked." (PMID 37020597, 2023). "A study examining the effects of fructose on colon cancer liver metastases found that aldolase B (ALDOB), an enzyme that is involved in fructose metabolism, was upregulated in liver metastases compared with a normal colon and a primary colorectal cancer tumor." (PMID 36551528, 2022). "In line with our previous study, we verified a significant upregulation of ALDOB in colon cancer using TCGA and GTEx datasets." (PMID 33282950, 2020). "Elevated ALDOB levels correlate with unfavorable postoperative prognosis in CRC patients, colon cancer liver metastases, and response to neoadjuvant chemoradiotherapy in rectal cancer patients." (PMID 37816733, 2023). "We thus compared with the same gene expressions (up-regulated transcripts: SLC16A4, DSC3, ALDOB, EPHX4, ARHGAP24; and down-regulated transcripts (MS4A12, TMIGD1, CASP5) in 5 colon cancer lines: HCT 116, Caco2, HT-29, Lovo, and C32." (PMID 25929336, 2015).
colorectal cancer (7 papers, 2017 to 2025). A primary or metastatic malignant neoplasm that affects the colon or rectum. "Interestingly, both univariate and multivariate regression analyses in our previous study revealed that high ALDOB expression was associated with poor overall survival and disease-free survival of colorectal cancer patients." (PMID 33282950, 2020). "Further experiments demonstrated that the upregulation of ALDOB promotes tumor progression by epithelial-mesenchymal transition in colorectal cancer." (PMID 33282950, 2020). "Furthermore, ALDOB‐mediated lactate production increases carcinoembryonic antigen‐related cell adhesion molecule 6 (CEACAM6) protein stability by inducing Kla, which promotes cell proliferation and 5‐FU chemoresistance in colorectal cancer (CRC) cells." (PMID 39417674, 2024).
Obesity (5 papers, 2021 to 2025). Accumulation of substantial excess body fat. "Therefore, the overconsumption of a HFD and associated obesity probably leads to the increase in plasma ALDOB abundance that we observed here in mice through liver damage." (PMID 33594989, 2021). "Previous studies have shown that plasma ALDOB levels were elevated in obesity and non-alcoholic fatty liver disease (NAFLD) in both humans and mice." (PMID 38044448, 2023).
liver cancer (4 papers, 2015 to 2025). An epithelial or non-epithelial malignant neoplasm that arises from the liver. "In studies on liver cancer, the significant reduction in ALDOB expression suggests its potential role in suppressing cancer development." (PMID 40520908, 2025). "Further research has shown that ALDOB inhibits the progression of liver cancer by reducing the activity of G6PD and thereby decreasing the functionality of the pentose phosphate pathway, closely correlating with patient prognosis." (PMID 40520908, 2025).
pancreatic cancer (4 papers, 2012 to 2024). "Metabolic classification suggests the GLUT1/ALDOB/G6PD axis as a therapeutic target in chemotherapy-resistant pancreatic cancer." (PMID 39588377, 2024). "The comparison revealed that ALDOB, SLC2A2, PC and PCK1 mRNA levels were significantly higher in the liver metastatic lesions in comparison to the primary pancreatic tumors." (PMID 22412968, 2012). "High glucose metabolism due to GLUT1/ALDOB/G6PD axis expression promotes drug resistance in pancreatic cancer, and inhibition of the GLUT1/ALDOB/G6PD axis may serve as a target for drug resistance therapy." (PMID 38297250, 2024).
Cirrhosis (3 papers, 2015 to 2025). A chronic disorder of the liver in which liver tissue becomes scarred and is partially replaced by regenerative nodules and fibrotic tissue resulting in loss of liver function. "A univariate analysis revealed that HBs and HBe antigens, cirrhosis, tumor size, micro-vascular invasion, macro-vascular invasion, encapsulation, BCLC stage, TNM stage, and ALDOB expression level were significantly correlated with RFS." (PMID 26376879, 2015). "Plasma proteome profiling of 48 patients with and without cirrhosis or NAFLD revealed six statistically significantly changing proteins (ALDOB, APOM, LGALS3BP, PIGR, VTN, and AFM), two of which are already linked to liver disease." (PMID 30824564, 2019).
clear cell renal cell carcinoma (3 papers, 2021 to 2025). "Nevertheless, it is still uncertain if there is a relationship between ALDOB levels, prognosis, and tumor-infiltrating lymphocytes in clear cell renal cell carcinoma (ccRCC)." (PMID 40852386, 2025). "Additionally, we also examined the difference of ALDOB expression in tissues of renal clear cell carcinoma with different pathological stages, and found that the ALDOB expression in tumor tissues of stage II/III was markedly lower than that of stage I/II (p < 0.001)." (PMID 40852386, 2025). "Similarly, decreased ALDOB expression has been observed in clear cell renal cell carcinoma." (PMID 36644641, 2022).
colon adenocarcinoma (3 papers, 2023 to 2025). "In fact, colon adenocarcinoma patients with high ALDOB mRNA expression had longer overall survival." (PMID 37190033, 2023). "Cancers such as cholangiocarcinoma (CHOL), esophageal carcinoma (ESCA), and kidney renal papillary cell carcinomas (KIRP) display down-regulated levels of ALDOB expression, whereas colon adenocarcinoma (COAD) and rectum adenocarcinoma (READ) produce higher levels." (PMID 40852386, 2025).
diabetes (3 papers, 2014 to 2024). "Aldolase fructose-biphosphate B (ALDOB), a marker of β-cell precursors, was upregulated in pre-diabetes and T2D donors as compared to donors without diabetes, indicating that mature β-cells may have reverted to a more immature stage of differentiation." (PMID 38731945, 2024).
Hepatic steatosis (3 papers, 2024 to 2025). Steatosis is a term used to denote lipid accumulation within hepatocytes. "The interactions between saroglitazar and ferulic acid with different enzymes and metabolites involved in metabolic dysfunction-associated fatty liver disease (MASLD), such as SORD, HK1, HK2, MgATP, KHK, HK3, ALDOB, ALDOC, and fructose-1-phosphate (F1P)." (PMID 40130107, 2025). "Its significance is evident from its role in promoting hepatic steatosis by targeting genes involved in lipid metabolism, such as fructose-bisphosphate B (ALDOB)." (PMID 38539937, 2024). "However, upon fasting, male and female AldoB-KO rats developed hepatic steatosis and hyperlipidemia due to impaired fatty acid oxidation (FAOx) and elevated de novo lipogenesis (DNL)." (PMID 41423081, 2025).
Hyperglycemia (3 papers, 2022 to 2025). An increased concentration of glucose in the blood. "An upregulation of ALDOB in human pancreatic β cells occurs upon the development of hyperglycemia and may contribute to the impairment of insulin secretion in humans." (PMID 35230239, 2022). "Because ALDOB, ALOX12, and KHK-A have been reported to promote fructose-induced cancer metastasis, we determined which of the three participated in hyperglycemia-induced cell migration." (PMID 38200154, 2024).
rectal cancer (3 papers, 2019 to 2025). A primary or metastatic malignant neoplasm that affects the rectum. "Elevated levels of ALDOB are associated with aggressive tumor characteristics, such as lymphovascular invasion and perineural invasion, highlighting its oncogenic role in rectal cancer." (PMID 40520908, 2025). "High expression of ALDOB in rectal cancer significantly correlates with poor patient prognosis, manifesting as reduced survival rates and weaker responses to chemotherapy and radiation therapy." (PMID 40520908, 2025).